FOXP3 (forkhead box P3)
Diseases named in the same sentence as FOXP3 in open-access papers (continued):
Sharing a sentence is not in itself a finding about the gene and the disease.
lupus (continued). "Lupus mice also showed a decreased frequency of CXCXR5+PD1+Bcl6+Foxp3+ TFR relative to TFH cells." (PMID 30348969, 2018). "Conversely, the anti-inflammation cells CD4+Foxp3+ Treg cells were significantly lower in B7-H4-KO BMDCs-induced lupus mice compared to control mice; thus, these results show that the lack of B7-H4 on DCs has changed the balance between T effector and Treg cells in this model." (PMID 29321778, 2017). "In addition, the FoxP3+ Helios+ T cells isolated from 20 lupus patients were shown to have lower IL-2 and IFNγ productions when compared with those from FoxP3+ Helios− T cells." (PMID 24864268, 2014). "In addition, hCDR1 increased the number as well as the function of CD4+CD25+Foxp3+regulatory T-cells in PBMC of lupus patients." (PMID 23555966, 2013). "In addition, we demonstrated the general importance of CD4+Foxp3+ Treg as physiologically relevant inhibitors of lupus by several approaches." (PMID 23446139, 2013). "Given the plasticity of the CD4+ T cell subsets, future studies should determine whether the defective regulations of FOXP3+ T cells and Th1/Th17 T cells in lupus patients are functionally related." (PMID 21708033, 2011). "This strongly suggests a defect in homeostatic regulation of FOXP3+ T cells in lupus patients." (PMID 21708033, 2011). "Monitoring urinary sediment mRNA levels of T-bet (key transcription factor of type 1 T helper cells), GATA-3 (key transcription factor of type 2 T helper cells), and FOXP3 (key transcription factor of regulatory T cells) could provide early indicators of disease flares in lupus patients." (PMID 39104393, 2024). "In addition, butyrate has also been shown to contribute to CD4 + Foxp3 + T cell induction in vitro, suggesting that this compound may attenuate lupus by altering the balance between Th17 cells and Treg cells." (PMID 33262998, 2020). "This study aimed to examine the phenotype and function of circulating CD4+Foxp3+ T cells in patients with systemic lupus erythematosus (SLE)." (PMID 32317002, 2020). "Intraperitoneal route of metformin gave a superior effect on the suppression of IFNγ levels and increasing FOXP3 mRNA expression compared to the oral route, and to the best of our knowledge this was the first study that observed this effect in pristane induced murine model of lupus." (PMID 34386197, 2020). "The protective effects have been validated in lupus-prone mice treated with a B lymphocyte gene vaccine that codes for IgG1 Fc-pCons, where early and repeated administration of the vaccine delayed proteinuria and enhanced survival remarkably as well as the expansion of Foxp3+ CD4+ Treg cells." (PMID 31379858, 2019). "Ex vivo expanded Foxp3+ regulatory T cells were injected intravenously into lupus mice, and the injected Foxp3+ regulatory T cells could be detected in the spleens, lymph nodes, livers, bone marrow, lungs, kidneys, and blood of the MRL/lpr mice, but mainly migrated into spleens and lymph nodes." (PMID 30760702, 2019). "Systemic lupus erythematosus (SLE) features a decreased pool of CD4+CD25+Foxp3+ T regulatory (Treg) cells." (PMID 28455530, 2017). "Recently, a subset of FOXP3+ cells with low CD25 expression was found to be increased in peripheral blood from systemic lupus erythematosus (SLE) patients, although its functional significance remains controversial." (PMID 28747257, 2017). "Finally, we show that exogenously expanded, adoptively transferred CD4+CD25+ T cells containing a mixed population of Foxp3+Tregsand co-expanded Foxp3−Teffs, to lupus prone B/W mice can enhance suppression of autoreactive lymphocytes and delay the development of autoimmune disease." (PMID 19551149, 2009). "In Treg cells from patients with lupus, elevated TET2 is involved in the expression of FOXP3, leading to an increased frequency of CD4+FOXP3+T cells in the circulation as well as in renal biopsy specimens." (PMID 40599235, 2025).
lupus (continued). "Recently, researchers have explored the overexpression of Foxp3 in CD19 CAR-T cells, which specifically target B cells that contribute to lupus pathology." (PMID 40481182, 2025). "In lupus murine models, the percentage of Tfh cells increased and the Tfr (CD4+CXCR5+FoxP3+) cells decreased in 16-week-old MRL/lpr mice." (PMID 37771588, 2023). "In lupus murine models, CD4+Foxp3+ Treg cells reduced the suppressive capacity against T cell proliferation, and adoptive transfer of Treg cells leads to lupus disease suppression and remission." (PMID 37771588, 2023). "Some scholars have studied lupus mice and found that the number of CD4 + CD25 + Foxp3 + Treg cells decreased in the advanced stage of the disease, suggesting that the decrease in the number of cells is related to the pathogenesis of lupus mice." (PMID 37474625, 2023). "In the context of T cell-associated genetic alterations, the Sle1a gene segment in the NZM2410 lupus-prone strain is responsible for the increased activation of conventional CD4+ T cells (Tcon) and for the low numbers of CD4+FoxP3+ Treg." (PMID 36389689, 2022). "To assess the regulatory role of CD38 in T-cells from a lupus-prone mouse (B6.MRL-Faslpr/J), we examined FoxP3 expression in three different subsets of CD3+CD4+CD25+ and CD3+CD4+CD25− T-cells, gated according to CD38 expression." (PMID 34769406, 2021). "Those FoxP3-Ly49+(CD158e+ in humans)CD122hiHelios+CXCR5+ CD8 Treg cells were decreased as a percentage of total CD8 T cell population in lupus, but such changes in proportion could be due to many reasons that cause shifts in various CD8 T cell subsets in lupus." (PMID 33936042, 2021). "In the clinic, low-dose IL-2 therapy has been shown to selectively expand FOXP3 Tregs and used successfully to treat chronic GVHD, hepatitis C virus–induced vasculitis, systemic lupus erythematosus (SLE), and type 1 diabetes." (PMID 34512640, 2021). "This study found a correlation between CD38 with FoxP3 expression and immunosuppressive molecules (CD69, IL-10, CTLA-4, and PD-1) in T-cells from lupus-prone mice (B6.MRL-Faslpr/J)." (PMID 34769406, 2021). "CAMKIV levels are higher in in vitro-cultured T cells from untreated lupus patients than in those from control patients, and silencing CAMKIV gene expression increases FoxP3 production after TGF-β stimulation." (PMID 33136553, 2020). "Baicalin could become a promising therapeutic medicine for the treatment of SLE because Baicalin stimulated expansion of Foxp3+ regulatory T cells and ex vivo expanded Foxp3+ regulatory T cells could be used to treat lupus." (PMID 30760702, 2019). "Recently, a subset of FOXP3+ CD4+ T cells with low expression of CD25 was reported to be increased in peripheral blood of autoimmune systemic lupus erythematosus (SLE) patients, a finding that was later expanded to the peripheral blood of multiple sclerosis and rheumatoid arthritis patients." (PMID 28747257, 2017). "We proved that CD4+CD25+Treg cells require FoxP3+-expressing CD8 cells, induced by tolerogenic peptide to suppress lupus activity." (PMID 24475019, 2014). "In addition it has been shown that proportions but not absolute numbers of Foxp3+Helios+ T cell are increased in systemic lupus erythematosus (SLE) patients and that Foxp3+Helios- T cells are capable of effector cytokine production." (PMID 24774748, 2014). "IL-10–producing FOXP3– (non-Treg) CD4+ T cells are expanded in lupus, including in W.Yaa mice, and the frequency of these cells was not affected by DON." (PMID 40956613, 2025). "The study demonstrates their impact to reduced anti-dsDNA, ANA, and anti-RNP antibodies, alleviated proteinuria and disease severity, boosted CD4+ CD25+ FoxP3+ Tregs, lowered IL-6, and elevated IL-10 and TGF-β, collectively ameliorating SLE symptoms in pristane-induced lupus mice." (PMID 40534849, 2025).
lupus (continued). "The therapeutic efficacy of CD4+Lrig1+ T cells was confirmed in chronic IBD and lupus genetic-animal model through the adoptive transfer, which is comparable to that of CD4+Foxp3+ T cells in the IBD model and CD4+CD25+ T cells or methylprednisolone in the lupus-prone model." (PMID 37666819, 2023). "Specifically, lowered numbers of CD8+ Treg cells have been reported in patients with systemic lupus erythematosus (SLE) and recovery of CD8+FOXP3+ Treg cells after transplantation of autologous hematopoietic progenitor cells has been associated with good control of disease activity." (PMID 35296082, 2022). "Silencing of CAMKIV increases Foxp3 production upon TGF-β stimulation from untreated lupus patients, indicating that CAMKIV acts as a negative Tregs regulator." (PMID 33995416, 2021). "T cell-specific Egr2 conditional knockout (CKO) mice develop progressive lupus-like autoimmunity with no impact on the development of Foxp3-dependent CD25+ Tregs." (PMID 29535721, 2018). "Our data demonstrated that eTreg and Foxp3+nonTreg frequencies correlate significantly with disease activity in systemic lupus erythematosus patients." (PMID 30009168, 2018). "Such cells have been reported in the blood of lupus patients, and therefore further work is required to understand the co-regulation of CD25 and FOXP3 expression on Tregs, and how this may become dysregulated." (PMID 25092890, 2014). "In renal tissue, during active lupus, increasing CD8+FoxP3+ T cells may inhibit T proliferation by cell-cell contact and increase production of suppressive cytokine IL-10." (PMID 24475019, 2014). "Nonetheless, these correlations between FOXP3 expressing T cells and memory T cells did not exist in lupus patients, while a positive correlation between CD25+ FOXP3- CD4+ T cells and memory T cells was maintained." (PMID 21708033, 2011). "It is of note that the numbers of CD4/CD8 double negative cells or their ratio to CD4/CD25/Foxp3 regulatory T cells are usually taken as a surrogate marker of the autoimmune process in experimental lupus." (PMID 21637713, 2011). "As the TC lupus-prone model, W.Yaa mice presented an expanded population of CD4+CD44+FOXP3–CXCR5+BCL6+CD162lo/–PD-1+ Tfh cells as well as follicular Tregs (CD4+CD44+FOXP3+CXCR5–BCL6–CD162lo/–PD-1+ Tfr), with a skewed Tfh/Tfr ratio, none of which were altered by DON." (PMID 40956613, 2025). "This is in line with a study from Golding and colleagues that showed that Helios-expressing Foxp3+ Tregs in systemic lupus erythematosus patients did not produce effector cytokines, and they still failed to fully protect the host from intense self-reactive B- and T-cell responses." (PMID 38473756, 2024). "In patients with systemic lupus erythematosus (SLE), in vitro experiment indicated that chloroquine could rebalance Th17 cells and Treg cells, while in vivo study showed that hydroxychloroquine treatment restored the balance of the immune system and increased the levels of FoxP3 in Treg cells." (PMID 33907514, 2021). "It is important to note that lupus CD4+ T cells were primed to receive and activate IL-2 signaling as evidenced by the upregulation of CD25 and enhanced IL-2-induced STAT5 phosphorylation during Treg differentiation even though the CD4+CD25+FOXP3+ Treg population was depleted in SLE patients." (PMID 33763079, 2021). "A subset of CD27+CD25high Vδ1 T cells, expressing FoxP3 similarly to regulatory CD4+ T cells, was reported in patients with systemic lupus erythematosus (SLE)." (PMID 28713381, 2017). "Although a previous report in patients with systemic lupus erythematosus shows that dexamethasone enhances Foxp3 expression without inducing a higher antiproliferative function, we demonstrate here that BUD reduced T lymphocyte proliferation upon allergen stimulation in allergic asthmatics." (PMID 23251336, 2012).
lupus (continued). "Although CD4+CD25+FOXP3+ Treg population was depleted, CD25 was upregulated on lupus CD4+ T cells, resulting in diminished proportion of CD4+CD25+FOXP3+ Treg cells among the CD4+CD25+ cells in SLE." (PMID 33763079, 2021). "Indeed, in PBMC cultures from inactive lupus patients and healthy subjects, addition of the histone peptide epitopes induced CD4+CD25highFoxP3+ or CD4+CD45RA+FoxP3low Treg cells, as well as CD8+CD25+FoxP3+ Treg cells with stable FoxP3 expression and suppressive activity." (PMID 33936042, 2021). "In consideration to the clinical translation of a Treg-based immunotherapy of SLE, we explored the potential of CD4+Foxp3+ Treg to maintain disease remission after induction of remission with an established cyclophosphamide (CTX) regimen in lupus-prone (NZBxNZW) F1 mice." (PMID 23446139, 2013). "Dex drug and W treatment did not affect Tregs (CD4+ CD25+ FOXP3+) and Bregs (CD5+ CD1d+) in lupus mice." (PMID 40158179, 2025). "increasing the percentages of FOXP3-negative Tr1 cells in both spleen and MLN suggests a possible probiotic-mediated control of inflammation that may happen in both MRL/lpr mice and lupus patients." (PMID 35967418, 2022). "However, Yang and colleagues reported that the phenotype and functional activity of Tregs were scarce on CD4 + CD25-Foxp3 + in lupus patients, that not all CD4 + Foxp3 + T cells have protective suppressive function." (PMID 33013906, 2020). "Thus, hCDR1 down regulated (in vivo and in vitro, in murine SLE models and in human lupus) pro-inflammatory cytokines, apoptotic factors, B-cell stimulatory factors (BAFF/BLyS) and up regulated immunosuppressive cytokines with the induction of CD4+CD25+FoxP3+regulatory T-cells." (PMID 23555966, 2013). "Interestingly, Gal-9 failed to expand Foxp3+ Tregs in MRL/lpr lupus-prone mice, suggesting that this is attributed to T cell abnormality in MRL/lpr lupus-prone mice." (PMID 23585851, 2013). "Recently, a subgroup of CD4+FoxP3+ T cells negative for CD25 has been detected in multiple immune regulatory diseases, such as systemic lupus erythematosus (SLE), HIV and Mycobacterium tuberculosis infection, and non-Hodgkin lymphoma (NHL)." (PMID 36064312, 2022).
Allergy (129 papers, 2008 to 2026). An allergy is an immune response or reaction to substances that are usually not harmful. "While similar findings on pathogenic Th2A cells have been published for other allergies, the role of antigen-specific FOXP3+ populations is less clear." (PMID 39782691, 2025). "In this study, we applied this approach to induce immune tolerance by converting pathogenic CD4+ T cells into Foxp3+ Tregs, thereby extending the therapeutic potential of AP-EVs from cancer to autoimmune and allergic diseases." (PMID 41410284, 2025). "Recent findings have also further described the induction of FOXP3, a Treg-specific transcription factor, and its dependence on DNA methylation and histone modifications in susceptibility to allergic disease, particularly at the maternal–fetal interface." (PMID 38256371, 2024). "Studies have also shown that protection from the development of allergic diseases mediated by microbial exposure in utero is associated with increased Treg function in neonates, FOXP3 expression and decreased methylation of the FOXP3 gene." (PMID 38256371, 2024). "It was also shown that methylation profile of IL4, IL5, IL10, IFNG and FOXP3 was associated with environmental exposures and the direction of methylation dynamics differed depending on the presence and types of allergy symptoms." (PMID 37520545, 2023). "Collectively, we showed that Nr4a factors transcriptionally regulate iTreg cell differentiation in part, by positively regulating Foxp3 expression, while repressing allergy-associated cytokine genes in a Foxp3-independent manner." (PMID 33665581, 2021). "In contrast, tolerance induction and cessation of allergy was associated with TSDR FOXP3 demethylation." (PMID 30602375, 2019). "Several genetic studies implicated the polymorphisms of Foxp3 in the risk of autoimmune and allergic diseases and demonstrated significant gender‐based differences in the distribution of Foxp3 polymorphisms." (PMID 30710380, 2019). "In contrast, hypermethylation of FOXP3 has been associated with reduced Treg function and development of allergy." (PMID 28933365, 2017). "Collectively, the present study proposes a novel mechanism by which NP such as PS50G, modulate the adaptive immune response by altering TNFR2+Foxp3+ Treg homeostasis, thereby decreasing susceptibility to allergic disease." (PMID 29312323, 2017). "In contrast, hypermethylation of the FOXP3 gene has been associated with reduced Treg function and allergy." (PMID 27175277, 2016). "In nasal polyps, whose association with allergy is still controversial, significantly increased infiltration of mTOR-activated inflammatory cells and decreased infiltration of FoxP3+ Tregs have been detected." (PMID 25071855, 2014). "Remarkably, intake of fresh unpasteurized cow’s milk exhibits an allergy-preventive effect in farm children associated with increased FoxP3+ Treg numbers." (PMID 25071855, 2014). "It is clear that individuals with defective or suboptimal Foxp3 expression due to mutations in Foxp3 gene or in genes that promote Foxp3 expression such as STAT5b are susceptible to allergic diseases." (PMID 24886492, 2014). "Similarly, the association of the FOXP3 gene methylation with milk’s allergy status in young allergic patients was observed." (PMID 37520545, 2023). "Another explanation for the lower FOXP3 methylation could be that in the developing immune system, the inflammatory processes associated with the development of allergies start to arouse an earlier response, whereas nothing is happening in healthy children." (PMID 37520545, 2023). "However, no other associations with pre-diagnostic glioma were found in any of the other allergy related transcription factors that were investigated (forkhead box p3 (FOXP3), signal transducer and activator of transcription 3 (STAT3) and STAT6)." (PMID 37265788, 2023).